IGFBP3 (insulin like growth factor binding protein 3)
Diseases named in the same sentence as IGFBP3 in open-access papers (continued):
Sharing a sentence is not in itself a finding about the gene and the disease.
liver fibrosis (13 papers, 2013 to 2025). "For example, IGFBP3 is a diagnostic and therapeutic target for alcoholic fatty liver and liver fibrosis." (PMID 38946724, 2024). "The upregulation of AUP1 and downregulation of IGFBP3 expression in liver cells are associated with the development of liver fibrosis and cirrhosis." (PMID 39083563, 2024). "As reported, IGFBP3 is a liver fibrosis progression‐associated protein; however, its role in liver fibrosis is currently inconclusive." (PMID 38946724, 2024). "Researchers have found that IGFBP3 is also associated with some fibrotic diseases, including lung and liver fibrosis." (PMID 36997948, 2023). "Taken together, lncRNA Snhg12 can promote TGF‐β1‐induced mHSCs proliferation and activation and subsequently advances the liver fibrosis process by up‐regulating IGFBP3 expression." (PMID 38946724, 2024). "In conclusion, LncRNA Snhg12 mediates liver fibrosis by targeting IGFBP3 and promoting its protein stability, thereby promoting mHSC proliferation and activation." (PMID 38946724, 2024). "In this study, the expression level of Igfbp3 was shown to be increased within mouse liver fibrosis tissues by bioinformatics analysis and positively correlated with Snhg12 expression." (PMID 38946724, 2024). "Moreover, the results of cellular experiments showed that IGFBP3 was significantly up‐regulated during HSC activation; animal experiments revealed that silencing IGFBP3 suppressed the activation of HSCs and the development of hepatic fibrosis." (PMID 38946724, 2024). "Notably, lncRNA Snhg12 and Igfbp3 expression levels exhibited a positive correlation within human and mouse liver fibrosis expression datasets (GSE84044, GSE123932, and GSE207857)." (PMID 38946724, 2024). "In contrast, overexpression of Snhg12 could boost HSC proliferation and activation and exacerbate liver fibrosis by up‐regulating IGFBP3 expression." (PMID 38946724, 2024). "In summary, this study underlines for the first time that lncRNA Snhg12 expression is increased within liver fibrosis tissues of mice, and the Snhg12/IGFBP3 axis could promote liver fibrosis by promoting HSC proliferation and activation." (PMID 38946724, 2024). "Therefore, more studies are warranted to explore the effect of IGFBP3 on liver fibrosis and related molecular mechanisms." (PMID 38946724, 2024). "“lnc Snhg12/IGFBP3 axis promote liver fibrosis by promoting HSC proliferation and activation”." (PMID 38946724, 2024). "It has been reported that IGFBP3 is a marker of culture‐induced HSC activation, and could be used as a diagnostic and therapeutic target for alcoholic fatty liver and liver fibrosis." (PMID 38946724, 2024). "Nevertheless, after performing a binary logistic regression, the IGF-1/intact IGFBP-3 ratio did not remain robustly associated with NASH or liver fibrosis (p = 0.06 unadjusted and p = 0.08 after adjusting for BMI and age)." (PMID 36831184, 2023). "Selective in vivo modulation of IGFBP3 could perhaps prevent the evolution of mild to more severe liver fibrosis." (PMID 24358328, 2013). "Therefore, Igfbp3 was selected in our study to further elucidate its role in mouse liver fibrosis." (PMID 38946724, 2024). "In addition, the IGF-1/intact IGFBP3 ratio is reduced in patients with liver fibrosis." (PMID 35154570, 2022). "In a carbon tetrachloride-induced liver fibrosis mice model, IGFBP-3 and DKK1/3 generated from AMSCs prevented the activation of hepatic stellate cells by suppressing the Wnt/β-catenin signaling pathway, decreasing liver fibrosis in mice." (PMID 37711653, 2023). "Recent reports suggest that IGF-1 biodisponibility might be decreased during disease progression toward NASH and liver fibrosis and advance IGF-1/intact IGFBP3 ratio as a fibrosis predictor." (PMID 34249975, 2021).
acromegaly (12 papers, 2008 to 2024). Acromegaly is an acquired disorder related to excessive production of growth hormone (GH) and characterized by progressive somatic disfigurement (mainly involving the face and extremities) and systemic manifestations. "Because of their stability and low diurnal variation compared to GH, IGF-1 and IGFBP-3 levels are used to screen for GH secretory disorders, including gigantism, acromegaly, and GH deficiency, and to monitor GH treatment for short stature." (PMID 39403490, 2024). "The aim of the study was to evaluate the association of the IGFBP3 gene polymorphism with clinical features and surgery outcomes in acromegaly." (PMID 30619084, 2018). "First, this was one of the first acromegaly case-control studies examining the relationship between the IGFBP3 -202A/C polymorphism and acromegaly risk." (PMID 30290787, 2018). "Logistic regression analysis showed a significant association between IGFBP3 genotype and a decreased risk of acromegaly under the additive model (AA vs. AC vs. CC)." (PMID 30290787, 2018). "The study also recruit 142 healthy controls, and the second aim of the study was to compare the incidence of the IGFBP3 polymorphism in patients with acromegaly vs the general population." (PMID 30619084, 2018). "In order to analyze the association between the SNP and acromegaly laboratory measurements, patients were compared in three or two groups in accordance with IGFBP3 genotypes." (PMID 30619084, 2018). "Several studies have shown an association between the IGFBP3–202 A/C polymorphism and both the clinical features and therapeutic responses of acromegaly patients." (PMID 30290787, 2018). "In the stratification analysis based on sex, we evaluated the association between the IGFBP3 genotype and acromegaly risk in female and male individuals." (PMID 30290787, 2018). "In summary, this was the first study that explored the relationship between the IGFBP3 -202A/C polymorphism and a predisposition to acromegaly in a Chinese population." (PMID 30290787, 2018). "Because the frequency of genotypes varies among different populations and ethnicities, several studies focused on the association of IGFBP3 with acromegaly, obtaining different results." (PMID 30619084, 2018). "In conclusion, our study was the first to evaluate the association of the IGFBP3-202A/C (rs2854744) polymorphism with acromegaly in a Chinese population." (PMID 30619084, 2018). "First, as the mechanism of acromegaly is dramatically complex and we only concentrated on the IGFBP3 polymorphism, this result cannot completely explain the clinical phenotype." (PMID 30619084, 2018). "We also investigate the difference in IGFBP3 polymorphism between acromegaly and general population." (PMID 30619084, 2018). "Our findings revealed that IGFBP3 genetic variants are associated with acromegaly risk." (PMID 30290787, 2018). "At first, we hypothesized that the AA genotype at the − 202 site of the IGFBP-3 gene might be associated with a decreased risk of acromegaly." (PMID 30290787, 2018). "We found that IGFBP3 genetic variants were significantly correlated with an altered risk of acromegaly and that allele C of rs2854744 was strongly correlated with a decreased risk of acromegaly in the Han Chinese population." (PMID 30290787, 2018). "Therefore, we aimed to examine the correlation of IGFBP3 genetic polymorphisms at the -202 site with the susceptibility to acromegaly and its different subtypes in the Han Chinese population." (PMID 30290787, 2018). "This study is one of the first to show that the IGFBP3 polymorphism may have an influence on serum levels and that the C allele of rs2854744 is associated with a reduced risk of acromegaly." (PMID 30290787, 2018).
acromegaly (continued). "Some cell culture studies showed that IGFBP3 plays a vital role in cell survival or apoptosis in various microenvironments; meanwhile, several clinical studies have indicated that variations in the IGFBP-3 genotype were associated with acromegaly risk and clinical features." (PMID 30619084, 2018). "Furthermore, there were significant associations between IGFBP3 genotype and decreased acromegaly risk under the additive (OR 0.385, 95% CI 0.206–0.72) and dominant (OR 0.364, 95% CI 0.168–0.785) models in females." (PMID 30290787, 2018). "In addition, we evaluated the association of the common polymorphism of IGFBP3 with the susceptibility to acromegaly, as well as with the susceptibility in subgroups of acromegaly." (PMID 30290787, 2018). "Therefore, in the current study, we aimed to investigate whether the −202A/C polymorphism of IGFBP3 constitutes a risk factor for acromegaly." (PMID 30290787, 2018). "Genetic polymorphism of IGFBP3 may be involved in the development of acromegaly." (PMID 30290787, 2018). "However, the effect of IGFBP3 gene polymorphism on acromegaly is less clear." (PMID 30290787, 2018). "A total of 36 blood samples from acromegaly patients before treatment were collected and tested for IGFBP3 levels; 27 patients had the AA genotype, 7 patients had the AC genotype, and only 2 patients had the CC genotype." (PMID 30290787, 2018). "On the other hand, the IGFBP3-202A/C genotype among patients with acromegaly vs. controls had trend toward statistically significant difference (P = 0.056)." (PMID 30619084, 2018). "IGFBP-3 was once considered to be a potential biochemical marker of excess GH in patients with suspected acromegaly." (PMID 26906713, 2016). "The concentration of IGFBP3, the main IGF carrier protein, is usually increased in patients with acromegaly, but this marker offers little further diagnostic information." (PMID 18578866, 2008). "IGFBP-3 levels may assist in the diagnosis and monitoring of acromegaly as there is a direct correlation between IGFBP-3 levels with IGF-1." (PMID 33803429, 2021). "Ultimately, these results suggested that IGFBP3 may be involved in the acromegaly development." (PMID 31818039, 2019). "However, there was not an association between IGFBP3 genotype and acromegaly risk in male individuals." (PMID 30290787, 2018). "We studied 100 patients with acromegaly in SRLs (72 F; median age 64 years, IQR 53.5–71 years; median IGF-I 209 ng/ml, IQR 158.5–268.5 ng/ml; median IGF-I ULN 0.79, IQR 0.64–1.15; median IGFBP-3 2.6 μg/l, IQR 2.2–3.2 μg/l)." (PMID 35748978, 2022). "We also examined various relationships between the IGFBP3 genotypes and glucose, lipid, phosphorus, kidney index, tumor volume, plasma GH level, and plasma IGF-1 before and after surgery in patients with acromegaly." (PMID 30619084, 2018). "Serum from the cat suffering from acromegaly contained significantly higher levels of IGF-I, IGFBP-3 and IGFBP-5 than serum from healthy and from diabetic cats." (PMID 27907059, 2016).
Cognitive impairment (12 papers, 2014 to 2024). Abnormal cognition is characterized by deficits in thinking, reasoning, or remembering. "The CSPG/HSPG serglycin (SRGN), hyaluronan receptor CD44 and insulin‐like growth factor‐binding protein 3 (IGFBP3) were among the most consistently downregulated genes associated with both mild and severe cognitive impairment in subjects with SZ." (PMID 33070392, 2021). "The purpose of this study was to assess the levels of serum IGF-2 and its binding proteins IGFBP-3 and IGFBP-7 in schizophrenia patients and the associations of these proteins with schizophrenia psychopathology and cognitive deficits." (PMID 32191705, 2020). "Accordingly, serum IGFBP-3 concentrations were increased in AD and mild cognitive impairment (MCI) patients in comparison to controls." (PMID 26637371, 2015). "The increased transcription of Igfbp3 in the AD_HFD and H_H groups might be related to its cognitive impairment." (PMID 36352898, 2022). "Moreover, knocking down Vi4 showed the same trend as Igfbp3-sh, which increased neuronal apoptosis and worsen the motor and cognitive deficits in rats with HIE (P < 0.5)." (PMID 33262982, 2020). "The effect of cognitive impairment on plasma levels of BDNF, 3-NT, IGF-1, IGF-2 and IGFBP-3 was evaluated using Student’s t test." (PMID 34341419, 2021). "Moreover, Vi4 overexpression and miR-185-5p knock-out promote the neuron survival and neurite growth, and suppress the cell apoptosis, then further improve the motor and cognitive deficits in rats with HIE, while Igfbp3 interfering got the opposite results." (PMID 33262982, 2020). "Interestingly, a large scale clinical study has demonstrated a significant association between low IGFBP3 serum levels and cognitive impairment, independent of low IGF-I serum levels, in elderly male AD patients compared to patients with mild cognitive impairment (MCI) and normal controls." (PMID 24964199, 2014).
Hypoglycemia (12 papers, 2008 to 2025). A decreased concentration of glucose in the blood. "The other adverse effect of the use of rhIGF-1 observed in GH receptor-deficient patients is hypoglycemia, due to low levels of IGFBP3 and increased level of free IGF-1 available for binding to insulin receptors." (PMID 17676425, 2008). "In infants with history of hypoglycaemia, hyperbilirubinemia, poor growth, midline defects, microphallus, low IGF-1 and IGFBP-3, MPHD, such as TSH and ACTH deficiency, and/or an abnormal brain MRI, the diagnosis of GHD is possible without stimulation test." (PMID 35250894, 2022). "In this sense, the lack or deficiency of hormones may lead to acute and subacute consequences, such as hypoglycemia, growth retardation, mental-motor deficiency, disturbances in cognitive functions and cardiovascular system, indicating an important role of Igfbp3 in HIE." (PMID 33262982, 2020). "Our last specific question related to the risks (e.g. tumours, hypoglycemia, cardiac hypertrophy, other soft tissue overgrowth) and benefits (assessed by A1c) of recombinant human IGF-1 (rhIGF-1) or IGF-1/IGFBP3 composite in patients with pathogenic INSR variants." (PMID 37794082, 2023). "Serum samples were drawn for IGF-2, IGF-1, IGF binding protein 3 (IGFBP-3), insulin, proinsulin, and C-peptide prior to hypoglycemia correction." (PMID 40270996, 2025). "Her growth was suboptimal with a GH concentration of 0.6 ug/L in response to hypoglycaemia with an undetectable serum IGF-1 and a low IGFBP3 (0.75 mg/L; NR 0.8–3.9)." (PMID 32060556, 2020). "The serum GH concentration at the time of hypoglycemia was noted to rise to a mean level of 12.5 μg/liter whilst the mean IGF-1 and IGFBP3 concentrations were low at 29.2 ng/mL and 1.21 mg/L, respectively." (PMID 24228030, 2013). "GHR-KO pigs show important hallmarks of the human disease, including reduced levels of insulin-like growth factor 1 (IGF1) and IGF-binding protein 3 (IGFBP3), increased serum GH concentrations, postnatal growth retardation, juvenile hypoglycemia, and a progressive increase in total body fat." (PMID 33029223, 2020). "The precise mechanism of hypoglycemia in SRS and likewise IGF2 dysfunction is not clear to date, but several factors are discussed: IGF2 presumably is able to bind to both IGF1 and IGF2 receptors as well as the insulin receptor and interacts with IGFBP3, possibly influencing glucose homeostasis." (PMID 33922271, 2021).
triple-negative breast carcinoma (12 papers, 2013 to 2024). An invasive breast carcinoma which is negative for expression of estrogen receptor (ER), progesterone receptor (PR), and human epidermal growth factor receptor 2 (HER2). "The association between PS5pre and triple-negative breast cancer could be mediated via IGFBP-3 by two ways." (PMID 33859244, 2021). "A proliferative role for IGFBP-3 is observed in triple-negative breast cancer (TNBC) cells via modulating sphingosine kinase-1 (SphK1) localization to activate EGFR signaling." (PMID 39619437, 2024). "In contrast, IGFBP-3 stimulates proliferation in triple-negative breast cancer (TNBC) cells via EGFR activation." (PMID 39619437, 2024). "In triple-negative breast cancer, IGFBP3 is involved in the PARP-dependent DNA damage repair pathway through interacting with SFPQ and NONO." (PMID 37088808, 2023). "In triple-negative breast cancers, the levels of IGFBP3 are arguably high and results in a poor prognosis as estrogen represses IGFBP3." (PMID 28393842, 2017). "Once induced, IGFBP-3 promotes survival and proliferation in triple-negative breast cancer cells." (PMID 39619437, 2024). "Insulin-like growth factor binding protein-3 (IGFBP-3) exerts varying effects on estrogen receptor alpha (ERα)-positive and triple-negative breast cancer (TNBC) cells." (PMID 39619437, 2024). "E2 stimulates IGFBP3 expression in MCF-7 cells and both E2 and 4-OHT increased IGFBP transcript expression in MDA-MB-231 triple negative breast cancer cells transfected with ERα." (PMID 24534923, 2014). "The very first evidence for the IGF/IGF-IR-independent actions of IGFBP-3 was the identification of specific cell surface binding between IGFBP-3 and cell surface proteins and subsequent cell growth inhibition in Hs578T human triple negative breast cancer (TNBC) cells." (PMID 32443727, 2020). "In addition, the SFPQ/NONO heterodimer has been shown to interact with IGFBP3, which forms a complex with EGFR and DNA-PKcs in triple-negative breast cancer cells, contributing to the IGFBP3 dependent NHEJ." (PMID 32998269, 2020).
fibrosis (11 papers, 2008 to 2024). the formation of excess fibrous connective tissue in an organ or tissue in a reparative or reactive process. "The interferon-alpha signaling pathway is activated in the human degenerative annulus fibrosis via induction of 3 IFITs and other genes, such as IGFBP3." (PMID 29482621, 2018). "For cardiac tissue, the suppression of IGFBP3 could alleviate cardiac fibrosis and cardiac remodeling in diabetic cardiomyopathy." (PMID 36267414, 2022). "In respect of the role of the GH-IGF-I axis in the pathogenesis of general NAFLD/NASH, it has been reported that serum levels of GH, IGF-I, and IGF-binding protein 3 (IGFBP-3) were associated with hepatic steatosis and fibrosis in patients with NAFLD, even in the non-GH-deficient population." (PMID 28678199, 2017). "Some of the most significantly activated canonical pathways included hepatic fibrosis/hepatic stellate cell activation (CD14, COL1A1, FGFR2, IGFBP3, MMP2, and TGFBR1), and p38 MAPK signaling pathways (CREB1, PLA2G2A, TGFBR1)." (PMID 20540791, 2010). "Both IGFBP-3 and IGFBP-5 induce dermal fibrosis with IGFBP-5 exerting a more drastic phenotype than IGFBP-3." (PMID 19088866, 2008). "In the studied population, the total IGF-1/intact IGFBP-3 ratio remained significantly lower in individuals with fibrosis than in controls with milder or no histologic lesions in the liver (p = 0.04)." (PMID 36831184, 2023). "Importantly, both IGFBP3 and IGFBP5 contribute to extracellular (ECM) deposition in IPF and promote fibrosis in human skin maintained in organ culture, demonstrating direct relevance to the human disease." (PMID 32210969, 2020). "We therefore hypothesize that this high IGF1+IGF2/IGFBP3 molar ratio, resulting in high total (IGF1+IGF2) bioavailability, could slow down the evolution form HS to fibrosis or cirrhosis." (PMID 25117570, 2014).